MMP1 (matrix metallopeptidase 1)
Diseases named in the same sentence as MMP1 in open-access papers (continued):
Sharing a sentence is not in itself a finding about the gene and the disease.
cholesteatoma (2 papers, 2012). A pathologic process characterized by the proliferation of keratinizing squamous epithelium resulting in the accumulation of keratin and cells in the middle ear and/or mastoid. "In cholesteatoma matrix metalloproteinases MMP1, MMP9, MMP10, and MMP12 were up-regulated." (PMID 23285167, 2012). "Among the 811 up-regulated extramatrix protein genes, MMP1, MMP7, MMp9, MMP10 and MMP12 and their substrate Osteopontin (SPP1) were amplified and their expression was significantly higher in cholesteatoma than in external canal skin (logFC>10)." (PMID 23285167, 2012). "Additionally to these two isoforms, MMP1 and MMP3 activity in cholesteatomas were also assessed through zymography, and increased activity was seen only in the first isoenzyme." (PMID 22714856, 2012). "Real-time PCR of PI3, SPRR1B, LCN2 (lipocalin 2), MMP1, MMP9, MMP10, MMP12, SPP1, GJB2, Bcl-xl (BCL2L1), cIAP2 (BIRC3), S100A7A (koebnerisin), S100A9, SERPINB3, CEACAM6, KRT6B and SERPINB4 revealed that the expression levels of these proteins were higher in cholesteatoma than in external canal skin." (PMID 23285167, 2012).
chronic lung disease (2 papers, 2021 to 2025). According to the definitions of the American and British Thoracic Societies, including pulmonary functional tests, X-rays, and CT scans for items such as fibrosis, bronchiectasis, bullae, emphysema, nodular or lymphomatous abnormalities. "In summary, we have explored the crucial roles of angiogenesis and immunity in the onset and progression of ILD and COPD, and we identified COL10A1, EDN1, MMP1, and RRAS as potential novel therapeutic targets for chronic lung diseases." (PMID 40002743, 2025).
co-infection (2 papers, 2019). "Since HCV-dependent MMP-1 induction in HSC was augmented by HIV co-infection, we speculate that MMP1 induction in HSC could have a potential to play a profibrotic role." (PMID 30679661, 2019). "QPCR analysis showed that the expression trend of 10 genes between the co-infection and control groups (IL-17C, NFκB, AP1, C/EBPβ, CXCL1, CXCL8, MMP1, MMP3, GM-CSF, and MUC5AC) was consistent with the RNA-seq results." (PMID 31803158, 2019).
corneal ulceration (2 papers, 2011 to 2020). "Corneal ulceration results from the destruction of stromal collagen by MMPs and other proteases, and we have now shown that triptolide inhibits the expression of MMP-1 and MMP-3 induced by poly(I:C) in human corneal fibroblasts." (PMID 21364906, 2011). "Corneal fibroblasts (activated keratocytes) produce MMPs in response to certain stimuli, with collagenase (MMP-1), stromelysin (MMP-3), and gelatinase (MMP-2) enzymes having been shown to be secreted by these cells in response to stimuli associated with corneal ulceration." (PMID 21364906, 2011).
coronary aneurysm (2 papers, 2004 to 2022). Abnormal balloon- or sac-like dilatation in the wall of coronary vessels. "We investigated the association between MMPs and coronary artery aneurysm by measuring the levels of MMP-1 and MMP-3 (both of which represent markers of proteolytic activity) in patients with coronary artery disease, some of whom had coronary aneurysms (cases) and others who did not (controls)." (PMID 15482602, 2004).
cutaneous squamous cell carcinoma (2 papers, 2020 to 2022). "Activation of EPHB2 promotes the progression of cutaneous squamous cell carcinoma cells by accelerating the production of invasive proteinases like MMP13 and MMP1." (PMID 32102656, 2020).
dermatofibrosarcoma (2 papers, 2018 to 2022). "In dermatofibrosarcoma protuberance tumor tissues, MMP1 was found to be prominent in tumor-associated macrophages." (PMID 35037689, 2022).
dermatomyositis (2 papers, 2017 to 2022). Dermatomyositis (DM) is a type of idiopathic inflammatory myopathy characterized by evocative skin lesions and symmetrical proximal muscle weakness. "In addition, overexpression of MMP-9, and MMP-1 was detected in dermatomyositis and polymyositis." (PMID 36289739, 2022). "High MMP-1 and MMP-9 expression was detected in myositis, polymyositis, and dermatomyositis patients, and MMP-9 antibodies are found in nearly all inflammatory myopathies." (PMID 36289739, 2022).
dilatation (2 papers, 2016 to 2024). "The current study aims to identify the role of MMP-1, MMP-2, MMP-9, and the MMP inhibitor, TIMP-1, in identifying aortic dilation in children with BAV." (PMID 39408865, 2024). "Hence, the current study proposes to identify whether three MMPs, namely MMP-1, MMP-2, and MMP-9, and the MMP inhibitor, TIMP-1, could be used to predict aortic dilatation in children with BAV." (PMID 39408865, 2024).
enteropathies (2 papers, 2018 to 2019). "In the present study, there was a strong correlation (ρ = 0.70) between IL-6 and MMP-1, suggesting that this could be one mechanism through which NTMs could lead to tissue re-modelling in enteropathy." (PMID 29680481, 2018). "The induction of MMP-1 and cytokines by M. avium in small intestinal tissue from a tropical population suggests that environmental mycobacteria could contribute to the epithelial disruption seen in environmental enteropathy in exposed populations." (PMID 29680481, 2018).
epithelial dysplasias (2 papers, 1998 to 2010). "MMP-1 expression in stromal cells was considerably weak and strongly associated with high-grade and low-grade intraepithelial neoplasia within Barrett's mucosa as well as cancer cells." (PMID 20946664, 2010). "In certain epithelial dysplasias and lichen planus, MMP-1 and -2 mRNA expressions were detected in few fibroblasts under the basement membrane zone, but normal mucosa was completely negative." (PMID 9649139, 1998). "Compared to BE (GERD) without intraepithelial neoplasia or carcinoma, MMP-1 expression was significantly upregulated in BE with adjacent EAC and EAC without BE." (PMID 20946664, 2010). "The aim of our study was to investigate expression of collagenases MMP-1 and -13 in EAC (with and without associated BE) as well as non-dysplastic BE (without evidence of intraepithelial neoplasia and carcinoma) and ESCC." (PMID 20946664, 2010). "Similarly, 100% (n = 19/19) of the EAC without BE expressed MMP-1, 6 of 10 ESCC (60%), and 10 of 18 (56%) Barrett's biopsies without intraepithelial neoplasia or carcinoma stained positive for MMP-1." (PMID 20946664, 2010).
gastric adenocarcinoma (2 papers, 2010 to 2018). "In the same way, in gastric adenocarcinoma cell lines, ETV4 increases MMP1 and MMP7 expression and stimulates invasion in vitro." (PMID 29996935, 2018).
gastrointestinal mucositis (2 papers, 2022 to 2025). "Our findings demonstrate that 5-FU-induced gastrointestinal mucositis is associated with increased activation of MMP-1, -2, and -8." (PMID 40524059, 2025). "Our study has demonstrated that gastrointestinal mucositis induced by 5-FU increases the activity of the proteolytic enzymes MMP-1, MMP-2, MMP-8, and TIMP-1 in sera and tissues." (PMID 36290656, 2022).
gingival enlargement (2 papers, 2010 to 2024). "It has been suggested that azithromycin can improve DIGE by inhibiting cell proliferation and collagen synthesis and activating matrix metalloproteinases (MMP-1, MMP-2) in gingival fibroblasts from patients with Cyclosporine A-induced gingival enlargement." (PMID 39070408, 2024). "This notion is supported by the finding that fibroblasts derived from subjects with cyclosporine-A (CSA)-induced gingival overgrowth produce significantly lower levels of MMP-1 than fibroblasts derived from subjects without overgrowth." (PMID 20843335, 2010).
HCMV infection (2 papers, 2020). "HCMV infection can cause increased mRNA level of MMP1, and MMP1 can decompose the extracellular matrix and participate in tissue remodeling and metastasis." (PMID 32016349, 2020). "In particular, HCMV infection led mainly to the over-expression of CCL2, CCL3, CCL11, CXCR4, IL-1β, IL13, MMP1, MMP3, MMP9 and MMP13, SERPINA1, TNFα, and BMP7, and the gradual and constant downregulation of IL13RA2 (up to almost 800-fold at 14 days p.i.)." (PMID 32899126, 2020).
hematoma (2 papers, 2020 to 2022). A hematoma is a collection of blood from a vascular structure into an extravascular space. "Our analysis indicated that VEGF, PDGF-BB, TNF-alpha, MMP-9, IL-6, CCL2, IL-1 alpha, MMP-1, MMP-8, and IL-8 were DEGs between the hematoma fluid and the peripheral blood before surgery." (PMID 35207175, 2022).
hypopharyngeal carcinoma (2 papers, 2018 to 2022). Carcinoma, predominantly squamous cell, arising from the epithelial cells of the hypopharynx. "And MMP1 was also found to promote liver metastatic necrosis of hypopharyngeal cancer in vivo." (PMID 35426219, 2022). "However, few research has focused on MMP1 expression and effect in hypopharyngeal cancer specifically." (PMID 35426219, 2022). "MMP1 activated AKT pathway to promote proliferation and migration of hypopharyngeal cancer cells." (PMID 35426219, 2022). "Our experiment in vitro showed that the absence of MMP1 in hypopharyngeal cancer cells attenuated cell growth and migration." (PMID 35426219, 2022). "In this study, we verified that MMP1 promoted tumor progress and could serve as a biomarker in HNSCC, especially in hypopharyngeal cancer." (PMID 35426219, 2022).
Insulin resistance (2 papers, 2023 to 2025). Increased resistance towards insulin, that is, diminished effectiveness of insulin in reducing blood glucose levels. "Therefore, the upregulation of MMP1 following Mpro exposure may contribute to liver inflammation and insulin resistance not only through matrix remodelling but also via PAR1-mediated pro-inflammatory pathways." (PMID 40843809, 2025).
juvenile idiopathic arthritis (2 papers, 2019 to 2022). Juvenile idiopathic arthritis (JIA) is the term used to describe a group of inflammatory articular disorders of unknown cause that begin before the age of 16 and last over 6 weeks. "In the aqueous humor of juvenile idiopathic arthritis patients with anterior uveitis, the levels of MMPs (MMP1, MMP3, MMP9) are significantly higher than those in controls." (PMID 35274006, 2022). "Interestingly, it was recently shown that plasma MMP-1 was reduced after the introduction of exclusive enteral nutrition in patients with juvenile idiopathic arthritis, another disease where the involvement of the GI tract has been suggested." (PMID 30834110, 2019).
localized scleroderma (2 papers, 2012 to 2025). Localized scleroderma is the skin localized form of scleroderma characterized by fibrosis of the skin causing cutaneous plaques or strips. "Autoantibodies against MMP-1 were detected in both localized scleroderma and SSc, especially in morphea, and were associated with higher anti-nucleosome antibody levels and shorter disease duration." (PMID 41226358, 2025). "Supernatants of CI-stimulated PBMC from juvenile and adult diffuse cutaneous (dc)SSc patients significantly reduced MMP-1 production by SSc dermal fibroblasts, while supernatants of CI-stimulated PBMC from patients with localized scleroderma (LS) did not." (PMID 22367096, 2012).
lymphoma (2 papers, 2022 to 2026). A malignant (clonal) proliferation of B- lymphocytes or T- lymphocytes which involves the lymph nodes, bone marrow and/or extranodal sites. "The current study examined the prognostic value of MMP1 in DLBC lymphomas to check if it reflects invasive behavior, yet MMP9 expressed no significant value." (PMID 35083113, 2022).
malignant glioma (2 papers, 2010 to 2018). A grade III or grade IV glioma arising from the central nervous system. "Elevated levels of several MMPs, like for example MMP-1, -2, -7, -9, -11, -12, -14, -15, -19, -24 and -25 have been reported in malignant glioma samples from patients, suggesting that their expression is closely related to malignant progression in vivo." (PMID 21067565, 2010).
microphthalmia (2 papers, 2020 to 2021). Congenital or developmental anomaly in which the eyeballs are abnormally small. "(2006) indicated that O. humifusa extracts (OHE) effectively inhibited the transcription factor associated with microphthalmia, reduced-matrix metalloproteinase-1 (MMP-1), and phosphorylation of c-Jun N-terminal kinase (JNKs)." (PMID 34497316, 2021).
multiple myeloma (2 papers, 2022 to 2023). "Interestingly, Bortezomib (a proteasome inhibitor used in humans as a therapeutic agent for multiple myeloma) has been shown to elicit an anti-fibrosis effect through a dual activity: an increase in MMP1 and MMP2 mRNA and proteins and a decrease in collagen 1a mRNAs and proteins." (PMID 35203262, 2022). "This indicates that the interaction between MMP-1 and p38/MAPK plays a crucial role in modulating the interplay between myeloma cells and BMSCs." (PMID 37823051, 2023). "This review focuses on the role of MMP-1, MMP-2, MMP-7, MMP-9, MMP-13, MMP-14, and MMP-15 and the four types of TIMPs in the invasion of myeloma cells, angiogenesis, osteolytic osteopathy, to offer some novel perspectives on the clinical diagnostics and therapeutics of MM." (PMID 37823051, 2023).
myocarditis (2 papers, 2013 to 2022). Myocarditis is a condition that is characterized by inflammation of the heart muscle (myocardium). "The expressions of Mmp12, Gpnmb, and Atp6v0d2 were all enhanced in the myocarditis group compared to the control group, of which only Mmp1 and Gpnmb were shared with the hub gene list." (PMID 36226312, 2022). "The ratio of TIMP-1/MMP-1 or MMP-3 expression was significantly increased (P < 0.05) indicating an increase of deposition of collagen proteins at the later stage of CVB3 myocarditis." (PMID 24023968, 2013).
neurofibromatosis (2 papers, 2021 to 2022). A hereditary neoplastic syndrome in which tumors grow in the nervous system. "In the neurofibromatosis dermal cell lines, MMP-1 protein was downregulated, and this decrease can be restored by the HCQ." (PMID 35346242, 2022). "In neurofibromatosis 1, the mRNA and protein expression of MMP1 is markedly downregulated by an unknown mechanism(s)." (PMID 34011935, 2021).
neutropenia (2 papers, 2022 to 2025). A decrease in the number of neutrophils found in the blood. "Finally, reduced soluble E‐selectin levels showed the strongest but sole association with prolonged neutropenia, and reduced MMP‐1 was almost exclusively associated with prolonged thrombocytopenia after CAR‐T." (PMID 41368079, 2025).
non-alcoholic steatohepatitis (2 papers, 2023 to 2025). "Furthermore, MMP-1 expression was found to be increased in hepatic progenitor cells from the early stages of nonalcoholic steatohepatitis (NASH), likely due to inflammation and steatosis." (PMID 40572790, 2025). "Furthermore, MMP1 was found to be expressed in monocytes, Kupffer cells, and liver stellate cells early in the development of non-alcoholic steatohepatitis (NASH), as well as in the hepatocyte progenitor cells participating in the process of angiogenesis in advanced NASH." (PMID 36835545, 2023).
oral cavity cancer (2 papers, 2020 to 2022). A primary or metastatic malignant neoplasm involving the oral cavity. "The notable increase in salivary MMP-1 levels in oral cavity cancer patients from G0-1 to G3 and N0 to N2-3 suggests that salivary MMP-1 might be a useful indicator of OSCC prognosis." (PMID 32823758, 2020). "As MMP-1 was prominently elevated in oral cavity cancer patients compared with non-cancerous groups, we further analyzed salivary MMP-1 levels in patients according to overall stage." (PMID 32823758, 2020). "Moreover, salivary MMP-1 levels in stages I, II, III, and IV oral cavity cancer patients were higher than those in non-cancerous groups (HC and OPMD), with AUCs of 0.839, 0.908, 0.899, and 0.946, respectively." (PMID 32823758, 2020).
pancreatic ductal adenocarcinoma (2 papers, 2022 to 2023). An infiltrating adenocarcinoma that arises from the epithelial cells of the pancreas. "In the IHC of clinical samples, MMP1 was overexpressed in pancreatic ductal adenocarcinoma cells than paired normal pancreatic ductal cells." (PMID 37484321, 2023).
pancreatitis (2 papers, 2017 to 2024). Inflammation of the pancreas. "When comparing the pancreatitis against the healthy control group, arginase, cathepsin B, MMP1, −3, −9, and neutrophil, elastase demonstrated to have significant differences in measured fluorescence signal." (PMID 40292193, 2024). "Enzymatic activity of MMP1 was downregulated for the healthy control group and increased steadily for pancreatitis, metastatic pancreatic cancer, and localized pancreatic cancer, respectively." (PMID 40292193, 2024). "(A) qRT-PCR for Egf, Tgfα, Hbegf, Areg, Ereg, Mmp1, Mmp2, Mmp9, Mmp12 and Mmp14 expression in littermate control, iKras* pancreata 3 weeks post pancreatitis, iKras* and iKras*;CD11b-DTR pancreata 3 days post Kras* inactivation and DT treatment." (PMID 28980940, 2017). "All eight nanobiosensors (arginase, cathepsin B, cathepsin E, MMP1, MMP3, MMP9, neutrophil elastase, and uPA) were used to measure enzymatic activity in serum samples from four different disease groups: localized pancreatic cancer, metastatic pancreatic cancer, pancreatitis, and a ‘healthy’ control." (PMID 40292193, 2024).
periapical granuloma (2 papers, 2016 to 2021). Chronic nonsuppurative inflammation of periapical tissue resulting from irritation following pulp disease or endodontic treatment. "Indeed, the high matrix proteinase activity is a hallmark of periapical granulomas, and is supposed to derive from a combined action of multiple MMPs such as MMP-1, MMP-2, MMP-8, MMP-9, and MMP-131,28." (PMID 27556208, 2016). "On the other hand, a significant correlation of SNPs in MMP-1 was reported in periapical granuloma." (PMID 34539639, 2021).
peripheral arterial disease (2 papers, 2013 to 2020). A disorder of the arteries supplying the upper and lower extremity and the visceral organs. "In clinical studies, abnormal circulating levels of MMP-1, -2, -8, -9, and TIMP-1 were found in patients with Peripheral Arterial Disease; their increase was attributed to the presence of ischemic tissue." (PMID 31963569, 2020).
pituitary adenoma (2 papers, 2019 to 2024). "The major types of MMPs involved in pituitary adenoma invasion can be classified into collagenases (MMP-1), gelatinases (MMP-2 and MMP-9), stromelysins (MMP-3), and membrane type (MMP-14) according to their function and location." (PMID 30733705, 2019).
polycystic kidney disease (2 papers, 2020 to 2023). A usually autosomal dominant and less frequently autosomal recessive genetic disorder characterized by the presence of numerous cysts in the kidneys leading to end-stage renal failure. "Serum MMP1 was found to be significantly elevated in polycystic kidney disease." (PMID 37006258, 2023). "Several studies on polycystic kidney disease have revealed cystic kidneys tubules synthesize and secrete high levels of MMPs, especially MMP-2, MMP-1 and MMP-9." (PMID 33256255, 2020).
proliferative diabetic retinopathy (2 papers, 2016 to 2023). Advanced retinopathy due to diabetes mellitus characterized by the formation of new vessels in the retina. "There was a significant difference in MMP-1 concentration between the mild non-proliferative diabetic retinopathy (NPDR) group and the proliferative diabetic retinopathy (PDR) group (p = 0.012)." (PMID 27467659, 2016).
Pruritus (2 papers, 2012 to 2025). Pruritus is an itch or a sensation that makes a person want to scratch. "Alternate hypotheses regarding the origin of pruritus have included high serum immunoglobulin (Ig)E levels, concurrent filaggrin mutations leading to atopy, high expression of matrix metalloproteinase 1 (MMP1) causing imbalance of collagen degradation, and high cytokine interleukin (IL)-31 levels." (PMID 22515571, 2012).